CASC19 (cancer susceptibility 19)
Diseases named in the same sentence as CASC19 in open-access papers (continued):
Sharing a sentence is not in itself a finding about the gene and the disease.
tumor (12 papers, 2019 to 2025). "This aligns with our findings where CASC19’s down-regulation in LRRC8A-KO cells is associated with decreased tumor growth." (PMID 38909013, 2024). "Increased CASC19 expression is observed in colon cancer tissues and is associated with tumor size and metastasis." (PMID 33246471, 2020). "Meanwhile, we noticed that CASC15, CASC8, CASC9, and CASC19 were highly expressed in tumor samples and CASC16 and CASC18 were lowly expressed in tumor tissues." (PMID 40746360, 2025). "PIK3CD-AS2, AC092171.2, NRAV, ZFPM2-AS1, and CASC19 were risk factors in the m7GRLSig model; the expression of AC092171.2, NRAV, and ZFPM2-AS1 was significantly higher in tumor tissues in the TCGA cohort." (PMID 36661684, 2022). "We found that seven lncRNAs were highly expressed in tumor patients in the GTEx-TCGA database, and LncRNA CASC19/UCA1/LINC01094/LINC02323 were confirmed in both pancreatic cell lines and FISH relative quantity." (PMID 35047414, 2021). "To determine the contribution of CASC19 in the tumor radioresistance in vivo, we administrated cholesterol-modified siCASC19 or its control into the xenograft of CNE2R cells every 3 days during tumor growth." (PMID 33573349, 2021). "As expected, the intratumoral interference of CASC19 resulted in the increase in growth rate of the irradiated tumor in comparison with that of irradiated siNC cells in vivo, i.e., siCASC19 significantly reduced the radioresistance of CNE2R xenograft." (PMID 33573349, 2021). "A recent study showed that the expression of CASC19 responded with chemotherapeutic drugs in vivo and in vitro, but its role in tumor radiotherapy has been rarely reported." (PMID 33573349, 2021). "Our results demonstrate the relevance of the hub lncRNA CASC19 as predictor of tumor stage and overall survival, and suggest CASC19 is a novel biomarker of AGC and a potential therapeutic target." (PMID 31422382, 2019). "Similarly, in our present study, we have established that high CASC19 expression increases PSPC1 protein availability in the nucleus which promotes nuclear retention of β-catenin leading to tumor progression." (PMID 41023804, 2025). "Regulation of proteasomal ubiquitin-dependent protein catabolic process is one of the crucial pathways affected upon CASC19 silencing which might alter the stability of numerous tumor-suppressive and oncogenic proteins." (PMID 41023804, 2025). "Therefore, from the 77 epithelial lncRNAs which were upregulated in tumor samples we prioritized 11 candidates: AC016735.1, AC123023.1, BBOX1−AS1, CASC19, LINC00659, FEZF1−AS1, LINC00460, RP11−595B24.2, RP11−796E10.1, RP5−940J5.9 and RP11−350J20.12." (PMID 38740871, 2024). "Notably, we revealed the potential interaction between CASC19 and a metastatic reprogramming protein PSPC1 (paraspeckle component 1), which is known to be involved in the nucleocytoplasmic shuttling of oncoproteins like β-catenin to promote tumor progression." (PMID 41023804, 2025).
infection (4 papers, 2008 to 2021). The state of being infected such as from the introduction of a foreign agent such as serum, vaccine, antigenic substance or organism. "RT-qPCR (reverse-transcription quantitative PCR) assay illustrated that the mRNA level of CASC19 in the xenograft of CNE2R cells was effectively reduced by this siCASC19 infection." (PMID 33573349, 2021).
CASC19 also shares sentences with these, for which no sentence is quoted: colorectal cancer (3 papers); small cell lung carcinoma (3); adenocarcinoma (1); anaemia (1); autoimmune encephalitis (1); cerebellar ataxia (1); cerebellar degeneration (1); cervical cancer (1); cholangiocarcinoma (1); Cognitive impairment (1); encephalitis (1); female infertility (1); hepatocellular carcinoma (1); neuroblastoma (1); neurological diseases (1); neuropathy (1); peripheral neuropathy (1); prostate tumor (1); rhinitis (1); soft tissue tumors (1); testicular germ cell tumor (1).